MIR1296 (microRNA 1296)
Synonyms: hsa-mir-1296; MIRN1296; mir-1296
Gene: MicroRNA gene on chromosome 10 (63,372,957 to 63,373,048, reverse strand). Ensembl gene ENSG00000221063.
Gene Ontology:
Biological process: miRNA-mediated post-transcriptional gene silencing
Cellular component: RISC complex
Homologues: Orthologues: chimpanzee ptr-mir-1296 (100% identical), macaque mml-mir-1296 (100% identical), dog MIR1296 (97% identical), pig ssc-mir-1296 (89% identical), rabbit MIR1296 (71% identical).